COL10A1 (collagen type X alpha 1 chain)
Diseases named in the same sentence as COL10A1 in open-access papers (continued):
Sharing a sentence is not in itself a finding about the gene and the disease.
lymph node metastasis (6 papers, 2018 to 2025). "In CRC, COL10A1 overexpression is linked to perineural invasion, lymph node metastasis, and higher histological grade." (PMID 40826474, 2025). "The mRNA expression level of COL10A1 was significantly associated with tumor size (P = 0.003), lymphatic emboli (P = 0.007), lymph node metastasis (P = 0.000), serosal invasion (P = 0.004), AJCC stage (P = 0.000), and recurrence risk (P = 0.001)." (PMID 30154451, 2018). "COL10A1, one of the collagen family proteins, has been accumulated in tumors, and an earlier study found that COL10A1 was utilized to predict the probability of lymph node metastasis in bladder cancer." (PMID 35450397, 2022). "More COL10A1 is expressed in GC than in normal tissues, and this is distinctly related to T stage and lymph node metastasis." (PMID 35874675, 2022). "Meanwhile, it must be paid attention to that high expression levels of COL10A1 significantly affected the GC patients’ prognosis of having lymph node metastasis." (PMID 33371777, 2021). "The high expression of COL10A1 was obviously related to T stage (P = 0.025) and lymph node metastasis (P = 0.025)." (PMID 33371777, 2021). "The Kaplan–Meier curve in the Kaplan-Meier plotter database (P = 0.0371) and GSE84437 (P = 0.002) indicate that patients with high COL10A1 expression possess poor prognosis, specifically GC patients with lymph node metastasis have it." (PMID 33371777, 2021). "Besides, the high articulation of COL10A1 was identified with helpless forecast of patients with lymph node metastasis, while that of patients with low articulation of COL10A was better." (PMID 33371777, 2021). "On this premise, the connection between the statement of COL10A1 and clinicopathological boundaries was additionally examined, and it was discovered that high articulation levels of COL10A1 were fundamentally related to T stage and lymph node metastasis." (PMID 33371777, 2021). "Patients with higher expression of COL10A1 had a worse outcome due to lymph node metastasis." (PMID 33324550, 2020). "There was a positive correlation between COL10A1 expression and lymph node metastasis." (PMID 33324550, 2020). "Clinically, COL10A1 was demonstrated upregulated in LUAD patients, meanwhile, the expression level of COL10A1 was positive related to lymph node metastasis and poor prognosis." (PMID 33324550, 2020).
oral cancer (6 papers, 2021 to 2024). "Meanwhile, it has been documented in separate studies that tumour tissue has elevated COL10A1 gene expression contrasted with corresponding normal tissue in colorectal, lung and oral cancer cases." (PMID 39656597, 2024). "Oral cancer cells express low levels of miR-101-3p by targeting the collagen type X alpha 1 chain (COL10A1)." (PMID 36612314, 2023). "It was later discovered that the expression of exosomal miR-101-3p, which was produced from human bone marrow mesenchymal stem cells (hBMSCs), could inhibit oral cancer invasion and migration by downregulating COL10A1 (type X alpha 1 chain of collagen)." (PMID 37635248, 2023). "Exosomes delivered miR-101–3p in vitro and in vivo to inhibit the proliferation, invasion, and migration of oral cancer cell line TCA8113, as well as inhibit tumor growth by targeting and downregulating collagen type X alpha 1 chain (COL10A1) of the collagen family." (PMID 38994350, 2024).
prostate carcinoma (6 papers, 2011 to 2025). A carcinoma that arises from epithelial cells of the prostate gland. "However, the expression, prognostic significance, clinicopathological attributes and immune-related associations of COL10A1 in prostate cancer as well as in pan-cancer contexts remain poorly understood." (PMID 38147021, 2023). "COL10A1 overexpression can also influence immunotherapy response and resistance to radiotherapy and chemotherapy in prostate cancer patients through mechanisms involving endoplasmic reticulum stress." (PMID 41303526, 2025). "The clinicopathological features of 38 patients with prostate cancer and their correlations with the expression of COL10A1." (PMID 39656597, 2024). "We performed immunohistochemistry staining (IHC) for COL10A1 on 10 pairs of prostate cancer patient and benign prostate hyperplasia (BPH) tissues specimens." (PMID 38147021, 2023). "Our experiments demonstrated that the knockdown of COL10A1 leads to frustration of biological behaviors such as proliferation, migration and invasion of prostate cancer cells." (PMID 38147021, 2023). "It is noteworthy that the level of all immune infiltrating cells in prostate cancer was positively correlated with COL10A1." (PMID 38147021, 2023). "Subsequently, the biological functions of COL10A1 in prostate cancer were elucidated by experimental validation." (PMID 38147021, 2023). "The expression level of COL10A1 was markedly higher in prostate cancer tissues compared to adjacent tissues." (PMID 38147021, 2023). "The outcomes indicated that COL10A1 was expressed at a much higher level in the prostate cancer samples than it was in the BPH tissues." (PMID 38147021, 2023). "Together, these findings suggested that attenuating the COL10A1 can greatly suppress the aggressiveness of prostate cancer cells." (PMID 38147021, 2023). "In summary, the findings demonstrated the overexpression of COL10A1 in prostate cancer, corroborating the observations from the bioinformatic analysis and providing a foundation for subsequent experiments." (PMID 38147021, 2023). "COL10A1+Fib was predominantly localized to tumor tissues, with its abundance and expression level significantly higher in tumors than in normal tissues across all cancers except prostate cancer." (PMID 40826474, 2025). "Additionally, the expression level of COL10A1 in 4 pairs of prostate cancer tissues and adjacent tissues was observed via Western Blot." (PMID 38147021, 2023). "In addition, knockdown of COL10A1 in prostate cancer resulted in a substantial reduction in the proliferation, migration, and invasive potential of prostate cancer cells." (PMID 38147021, 2023). "It was revealed that at the protein level, except for LNCap, the expression of COL10A1 in the other three prostate cancer cell lines were markedly upregulated compared to RWPE-1 (normal prostate cells)." (PMID 38147021, 2023).
bladder cancer (5 papers, 2021 to 2025). "Our findings agree with those from others, as high COL10A1 expression was previously associated with a poor prognosis in five bladder cancer cohorts." (PMID 40792276, 2025). "Previous studies have shown that COL10A1 expression is upregulated in multiple solid cancers, including breast, lung, oesophageal, stomach, colon, and bladder cancers." (PMID 37974070, 2023). "In this study, we identified six ECM-related genes (CTHRC1, MMP11, COL10A1, FSTL1, SULF1, and COL5A3) that were associated with bladder cancer occurrence, tumor stage, and prognosis based on the bladder cancer tumor samples." (PMID 35450397, 2022). "Based on the TCGA dataset, the expression levels of COL10A1, COL5A3, CTHRC1, MMP11, and SULF1 in the bladder cancer tissues were higher than those in the normal bladder tissues." (PMID 35450397, 2022).
colon cancer (5 papers, 2014 to 2023). "The described results further established COL10A1 as a diagnostic marker for predicting progression of colon carcinogenesis, extending previous reports on this protein in the context of colon cancer." (PMID 36267978, 2022). "We present a sequential process for the identification and further validation of biomarkers for early detection of colon cancer that identifies COL10A1 protein levels in serum as a potential diagnostic candidate to detect both adenoma lesions and tumor." (PMID 25215506, 2014). "Remarkably, COL10A1 showed relevant enough differences between controls and colon cancer patients (p = 3.2×10−6) to be proposed as a potential diagnostic candidate." (PMID 25215506, 2014). "Furthermore, a historic study has already proposed COL10A1 serum protein levels to be a minimally invasive and indicative marker for colon cancer detection as compared to its absence in healthy patients." (PMID 36267978, 2022). "Elevated serum levels of COL10A1 were observed both for adenoma and colon cancer patients." (PMID 25215506, 2014). "After a subsequent prioritization, all tested genes (N = 23) were successfully validated in tissue, and one of them, COL10A1, showed relevant differences in serum protein levels between controls, patients with adenoma (p = 0.0083) and colon cancer cases (p = 3.2e-6)." (PMID 25215506, 2014).
age-related macular degeneration (4 papers, 2019 to 2024). Age-related loss of vision in the central portion of the retina (macula), secondary to retinal degeneration. "COL10A1 gene has been associated with age-related macular degeneration, myopia, and refractive error measurement." (PMID 38421723, 2024). "Furthermore, COL8a1 and COL10a1 are associated with age-related macular degeneration whereas mutations in COL8a2 can lead to Fuchs endothelial dystrophy, an impairment of vision." (PMID 38997817, 2024).
gastric adenocarcinoma (4 papers, 2022 to 2025). "Interestingly, the circulating expression level of COL10A1 is significantly increased in gastric adenocarcinoma patients and associated with poor survival in these cancers." (PMID 41373732, 2025). "Furthermore, studies have demonstrated the close relation between collagen genes and gastric adenocarcinoma, including COL10A1, COL1A1, COL1A2, and COL8A1." (PMID 35726219, 2022). "Altogether, our bioinformatics analysis study identified six upregulated DEGs (ADAMTS2, COL10A1, COL1A1, COL1A2, COL8A1, and BGN) between gastric adenocarcinoma and normal tissues based on four different microarray datasets." (PMID 35726219, 2022). "Consistent with much lower expression of COL10A1 mRNA, no protein expression was observed in colon adenocarcinoma or stomach adenocarcinoma by IHC." (PMID 39939916, 2025).
invasive breast carcinoma (4 papers, 2011 to 2025). A carcinoma that infiltrates the breast parenchyma. "COL10A1 showed an important role in differentiating in situ from invasive breast cancer and characterizing DCIS with a high risk developing IDC." (PMID 32043519, 2020). "COL10A1 mRNA expression was found to be the highest in breast invasive carcinoma (BRCA) and pancreatic adenocarcinoma (PAAD) tumors in TCGA." (PMID 39939916, 2025). "Stromal reaction to invasive breast carcinoma was associated with increased expression of genes encoding ECM components, proteolytic enzymes and adhesion receptors, including COL11A1, COL10A1, COMP, MMP11, FN1 and MFAP2, consistent with the abundant stromal remodeling observed by histology." (PMID 21611158, 2011).
stomach cancer (4 papers, 2020 to 2025). "The analysis showed that COL10A1 is up-regulated in gastric tumor tissue, and an increased expression is associated with poor prognosis." (PMID 41303526, 2025). "In previous studies, our team identified significant increases in the expression of several genes, including COL10A1, in gastric tumors compared to adjacent normal tissues." (PMID 41303526, 2025). "Therefore, in our study, we used the TCGA database to evaluate the expression of COL10A1 in gastric tumor tissue compared with normal adjacent tissue, and we also analyzed the COL10A1 prognosis value in GC patients." (PMID 41303526, 2025).
adenoma (3 papers, 2014 to 2022). A neoplasm arising from the epithelium. "The most promising one is the detection of COL10A1 in serum, which can identify adenoma and invasive cancer with high sensitivity and specificity." (PMID 25215506, 2014). "A few cancer-free subjects showed high levels of COL10A1 in serum, higher than the average for adenoma, indicating that other processes not related to colorectal lesions can increase COL10A1 levels." (PMID 25215506, 2014).
basal cell carcinoma (3 papers, 2021 to 2025). A carcinoma involving the basal cells. "ScRNA in basal cell carcinoma further identified COL10A1 as a CAF-specific gene, rarely expressed in other cell types, and enriched in highly invasive tumors." (PMID 40826474, 2025). "In basal cell carcinoma (BCC), scRNA-seq data from two independent datasets identified COL10A1-expressing stromal cells adjacent to infiltrative tumor regions, characterized by extracellular matrix remodeling features." (PMID 41303526, 2025).
cervical cancer (3 papers, 2023 to 2025). A primary or metastatic malignant neoplasm involving the cervix. "At the bulk level, COL10A1 was significantly upregulated in tumor tissues across all nine cancer types examined and its high expression was consistently associated with poorer OS, particularly in liver, gastric, breast, prostate, and cervical cancers." (PMID 40826474, 2025). "In cervical cancer cells, COL10A1 upregulation promotes proliferation, migration, and EMT processes through activation of N-cadherin and Vimentin via TGF-β/Smad signaling." (PMID 41303526, 2025). "It was also found that overexpression of COL10A1 promoted cell migration and invasion in cervical cancer, and silencing of COL10A1 inhibited cell proliferation, metastasis, and epithelial mesenchymal transition in cervical cancer by inactivating TGF-β/Smad signaling." (PMID 38063927, 2023).
chondrosarcoma (3 papers, 2011 to 2024). A malignant cartilaginous matrix-producing mesenchymal neoplasm arising from the bone and soft tissue. "IDH mutant chondrosarcoma demonstrated increased expression of collagen 10 alpha 1 (COL10A1) and matrix metalloproteinase 13 (MMP13) in our study." (PMID 38254737, 2024). "Furthermore, COL10A1 and MMP13 are involved in endochondral ossification, a process conserved in matrix-producing chondrosarcoma, and downregulated in dedifferentiated chondrosarcoma." (PMID 38254737, 2024). "Instead, chondrosarcoma cell lines were positive for late chondrocyte markers such as alkaline phosphatase (ALP) activity or COL10A1 expression, both of which were strongly increased by TGF-β1 treatment, indicating activation of an abnormal differentiation program in chondrosarcoma cells." (PMID 29044189, 2017). "Since proliferating chondrocyte/chondrosarcoma cells do not express Col10a1, these results suggest that in these cells, the proteins that bind to element A may contribute to the repression of Col10a1." (PMID 22072985, 2011).
dwarfism (3 papers, 2018 to 2022). "To illustrate the utility of the exploration module we selected a well-characterized experiment investigating the expression profile of a Col10a1 knock-in mutation mouse, which is a model of the Metaphyseal chondrodysplasia type Schmid (MCDS) form of dwarfism (GSE30628)." (PMID 30481257, 2019).
lung squamous cell carcinoma (3 papers, 2022 to 2025). "In lung squamous cell carcinoma (LUSC), METTL3-mediated m6A modification of COL10A1 mRNA in CAFs increases its stability, leading to elevated COL10A1 expression and increased secretion of COL10A1 by CAFs." (PMID 40176140, 2025).
non-small cell lung carcinoma (3 papers, 2020 to 2024). A group of at least three distinct histological types of lung cancer, including non-small cell squamous cell carcinoma, adenocarcinoma, and large cell carcinoma. "miR-384 inhibits autophagy and promotes apoptosis in non-small cell lung cancer cells through the downregulation of COL10A1 expression." (PMID 39198393, 2024).
pancreatic adenocarcinoma (3 papers, 2022 to 2025). "COL10A1 may be a novel diagnostic or therapeutic target in pancreatic adenocarcinoma." (PMID 37974070, 2023). "The results of our research indicated that COL10A1 promotes tumorigenesis by modulating CD276 in pancreatic adenocarcinoma." (PMID 37974070, 2023). "Significant overexpression of COL10A1 was observed in pancreatic adenocarcinoma tissues vs. normal pancreatic tissues according to GEPIA." (PMID 37974070, 2023). "The LinkedOmics database was utilized to perform survival analysis of pancreatic adenocarcinoma patients grouped based on COL10A1 expression level." (PMID 37974070, 2023). "Our research suggests that COL10A1 promotes pancreatic adenocarcinoma tumorigenesis by regulating CD276." (PMID 37974070, 2023). "Pancreatic adenocarcinoma tissues (n = 179) exhibited increased expression of COL10A1 compared to normal pancreatic tissues (n = 171) (P < 0.05)." (PMID 37974070, 2023). "The Cancer Genome Atlas (TCGA), Gene Expression Omnibus (GEO), and Gene Expression Profiling Interaction Analysis (GEPIA) data were employed to explore the expression of COL10A1 in normal and tumor tissues and its prognostic value in pancreatic adenocarcinoma." (PMID 36105715, 2022). "We further explored the role of COL10A1 in pancreatic adenocarcinoma." (PMID 37974070, 2023). "Besides, in pancreatic adenocarcinoma, the expression level of COL10A1 showed a significant positive correlation with tumor immune cell infiltration, biomarkers of immune cells, and expression of immune checkpoint molecules." (PMID 36105715, 2022).
renal fibrosis (3 papers, 2024 to 2025). A final common manifestation of a wide variety of chronic kidney diseases characterized by glomerulosclerosis and tubulointerstitial fibrosis. "Recent studies reveal that type X collagen is upregulated during renal fibrosis, and Col10a1 overexpression has been shown to promote aberrant ECM deposition following tubulointerstitial injury, thereby exacerbating renal fibrosis." (PMID 41302023, 2025). "Collectively, Col10a1 silencing mitigated renal fibrosis in I/R mice by inhibiting AKI-enhanced EMT in the kidneys." (PMID 38345033, 2024). "In this study, we detected significantly upregulated COL10A1 expression in the kidney tissues of I/R mice, indicating that upregulation of COL10A1 expression enhanced renal fibrosis." (PMID 38345033, 2024). "Our data indicate that KLF4 up-regulates miR-101 expression, leading to the downregulation of COL10A1 expression, inhibition of EMT and renal fibrosis during the pathogenic process of I/R-related renal fibrosis." (PMID 38345033, 2024). "Furthermore, we found that hypoxia increased COL10A1 and NGAL expression in HK-2 cells, further supporting the notion that COL10A1 contributes to renal fibrosis after AKI." (PMID 38345033, 2024). "Therefore, the miR-101/COL10A1 axis contributes to the pathogenesis of renal fibrosis in mice." (PMID 38345033, 2024). "Therefore, we tested whether KLF4 could modulate the miR-101/COL10A1 axis to affect renal fibrosis after AKI in mice and HK-2 cells." (PMID 38345033, 2024). "Our study shows that NU7441 suppresses COL10A1 expression in CAFs primarily through inhibition of the TGF-β/Smad signaling pathway, consistent with prior findings in renal fibrosis models." (PMID 40826474, 2025). "These novel findings unveil that KLF4 modulates the miR-101/COL10A1 axis to inhibit EMT and renal fibrosis after AKI." (PMID 38345033, 2024). "Collectively, these data suggest that KLF4-induced pre-miR-101 expression mitigates the hypoxia-enhanced Col10A1 expression, EMT, fibrosis, and tubular cell injury, contributing to renal fibrosis after AKI." (PMID 38345033, 2024). "Collectively, I/R-induced AKI promoted renal fibrosis in mice at 42 days post-induction by enhancing the EMT process in the kidney of mice and down-regulating the expression of KLF4 and miR-101 to enhance COL10A1 expression." (PMID 38345033, 2024). "However, there is no information on whether COL10A1 can modulate the process of EMT in renal epithelial cells during the process of renal fibrosis after AKI." (PMID 38345033, 2024).
Arthritis (2 papers, 2024 to 2025). Inflammation of a joint. "Elevation of ucOCN levels led to the downregulation of COL10a1 and MMP13 expression, accompanied by a marked improvement in cartilage integrity in murine models of arthritis." (PMID 40765832, 2025).